APP (amyloid beta precursor protein)
Diseases named in the same sentence as APP in open-access papers (continued):
Sharing a sentence is not in itself a finding about the gene and the disease.
Alzheimer disease (continued). "In this study we compare the performance of CNN algorithms to discriminate pre- and post-learning RCIs in the two groups of related animals, namely, the APP/PS1 mice which are a model of Alzheimer disease (AD) and their littermate kin (wild-type, WT)." (PMID 34711860, 2021). "Over the past 20 years, it has become clear that amyloid precursor protein (APP) is an important player in Alzheimer’s disease (AD), a common age-related neurodegenerative disorder that causes progressive memory and cognitive impairments." (PMID 34066808, 2021). "Most of the research on APP has been conducted in the context of Alzheimer’s disease (AD) and the processing of APP to amyloid β." (PMID 34066808, 2021). "The Amyloid Precursor Protein (APP) is the precursor that generates the Aβ peptide, whose accumulation is associated with Alzheimer’s disease (AD; Selkoe and Hardy, 2016)." (PMID 34515635, 2021). "By co-expression of human SERPINA3 with human APP in a transgenic murine model of Alzheimer’s disease, author found increased rate of disease progression indicating human ACT as amyloidogenic cofactor in AD pathogenesis." (PMID 33662018, 2021). "This review offers a comprehensive examination of the recent literature on the impact of APP/Abeta and tau on neuronal and network hyperexcitability in mouse models of Alzheimer’s disease." (PMID 33741601, 2021). "The amyloidogenic cleavage pathway of APP leads to production of amyloid-β (Aβ), deposited in the brains of Alzheimer’s disease (AD) patients." (PMID 35008544, 2021). "Amyloid β (Aβ) peptides generated from the amyloid precursor protein (APP) play a critical role in the development of Alzheimer's disease (AD) pathology." (PMID 34524402, 2021). "One of the FMRP partners is the APP mRNA, the main protagonist of Alzheimer’s disease (AD), thereby regulating its protein level and metabolism." (PMID 34760921, 2021). "Alzheimer’s disease (AD) is characterized by the aberrant processing of amyloid precursor protein (APP) and the accumulation of hyperphosphorylated tau, both of which are accompanied by neuroinflammation." (PMID 34371878, 2021). "BRI2 physically interacts with and modulates processing of amyloid-β precursor protein (APP), which bears relevance to Alzheimer's disease (AD) pathogenesis." (PMID 34416235, 2021). "Amyloid precursor protein (APP) metabolism is central to Alzheimer’s disease (AD) pathogenesis, but the key etiological driver remains elusive." (PMID 34663454, 2021). "SNX27/retromer downregulation is strongly linked to Down’s Syndrome (DS) via glutamate receptor dysfunction and to Alzheimer’s Disease (AD) through increased intracellular production of amyloid peptides from amyloid precursor protein (APP) breakdown." (PMID 33937239, 2021). "APBB stands for APP-binding family B and refers to the observation that all three Fe65 proteins bind to the amyloid precursor protein (APP) involved in the pathogenesis of Alzheimer’s disease (AD)." (PMID 34202290, 2021). "Alzheimer’s disease (AD) pathology is characterized by amyloid-beta, an extracellular product derived from amyloid precursor protein (APP), and intracellular aggregated tau57." (PMID 33483607, 2021). "They play a role in the trafficking of APP, and hence potentially play a role in Alzheimer’s disease." (PMID 32171335, 2020). "APP protein plays a central role in the development of Alzheimer’s disease; its expression, metabolism, splicing and secretion have been demonstrated to be regulated by ligands of the membrane tyrosine kinase receptors like BDNF." (PMID 32397504, 2020). "For example, cerebral blood flow (CBF) was shown to be decreased by ~30% in both patients with Alzheimer’s disease and mouse models of APP overexpression." (PMID 32857763, 2020). "On the contrary, in SY5Y neuroblastoma cells overexpressing APP, mimicking Alzheimer’s disease, treatment with ADAM9 pro-domains inhibited the activity of ADAM9 but reduced the production of Aβ peptides." (PMID 33096780, 2020).
Alzheimer disease (continued). "Most rodent models for Alzheimer’s disease (AD) are, therefore, based on the human APP sequence, expressed from artificial mini-genes randomly inserted in the rodent genome." (PMID 33076948, 2020). "VPS35 can regulate APP metabolism and Aβ formation, and its levels are reduced in Alzheimer’s disease (AD) brains." (PMID 31964406, 2020). "Among Alzheimer’s disease patients, decreased levels of APP processed by α-secretase have been reported." (PMID 33096780, 2020). "Amyloid precursor-like protein (APLP) 2 (APLP2) belongs to the protein family that includes amyloid precursor protein (APP) and APLP1 in mammals, which has been associated with Alzheimer’s disease pathogenesis." (PMID 32716039, 2020). "Recently, UCB-J was investigated in mice and more specifically in the amyloid precursor protein and presenilin 1 double-transgenic (APPswe/PS1DE9 [APP/PS1]) mouse model of Alzheimer disease." (PMID 32422902, 2020). "The amyloid beta (Aβ) precursor protein (APP) is an integral membrane protein recognized for its role in Alzheimer’s disease (AD) pathogenesis." (PMID 32576936, 2020). "In the transgenic APP/PS1 (APPswe/PS1dE9) mouse model for Alzheimer’s disease, depletion of microglia using a Csf1r inhibitor (PLX5622) results in an increase in parenchymal T cell numbers and a reduction of anti-inflammatory cytokines." (PMID 32856125, 2020). "In Chinese Familial Alzheimer’s Disease Network involving 404 pedigree, 13.1% of pedigrees carried PSEN1/PSEN2/APP mutations." (PMID 33188256, 2020). "Although little is known about liver-specific functions of APP, in the central nervous system it is a key driver of Alzheimer’s disease, as source of the amyloid- β-peptide (A β)." (PMID 33138772, 2020). "Amyloid precursor protein (APP) has been studied mostly in the context of Alzheimer’s disease (AD), however, recent reports show its importance in cancer and RA." (PMID 32435655, 2020). "As APP/PS1 mouse is a widely used animal model to study Alzheimer’s disease, we employed hippocampal tissues of APP/PS1 mice and age-matched wild type (WT) mice to generate ATAC-seq libraries." (PMID 32293531, 2020). "In the APP/PS1 mouse model of Alzheimer’s disease, which shows anxiety-like behaviour, photostimulating the pBLA–vCA1Calb1+ circuit ameliorates the anxiety in a Calb1-dependent manner." (PMID 31924799, 2020). "Substantial evidence has suggested that hyperglycemia provokes disease progression in mild cognitive impairment (Morris, Vidoni, Honea, Burns, & Alzheimer’s Disease Neuroimaging Initiative, 2014) and senile plaque formation in APP/PS1 transgenic mice." (PMID 32496635, 2020). "A molecular imaging probe to fluorescently image the β-site of the amyloid precursor protein (APP) cleaving enzyme 1 (BACE1) and cathepsin D (CatD) enzymes associated with Alzheimer’s disease (AD) was designed and synthesized." (PMID 31936569, 2020). "Some studies have also found that APP plays an important role in the pathogenesis of Alzheimer’s disease and is overexpressed in cancer cells, such as in nasopharyngeal carcinoma." (PMID 33194371, 2020). "Genetic susceptibility clearly appears to play an etiologic role for EOD, including APP and PSEN1/2 gene mutations for Alzheimer’s dementia (AD) and MAPT, GNR and C9ORF72 for frontotemporal dementia (FTD)." (PMID 33138082, 2020). "Recently, amyloid precursor protein (APP), which is known to have a central role in Alzheimer’s disease, was identified as a novel receptor of Slit." (PMID 33375263, 2020). "The Early-Onset form of Alzheimer’s Disease (EOAD) is due to mutations in chromosome 21, causing the formation of abnormal amyloid protein (APP), and mutations on chromosomes 14 and 1 leading to abnormal presenilins 1 and 2 which undergo cleavage of APP." (PMID 32438758, 2020). "Early synaptic deficits in the APP/PS1 mouse model of Alzheimer’s disease involved neuronal adenosine A2AR." (PMID 32357548, 2020).
Alzheimer disease (continued). "Senile plaques, the hallmarks of Alzheimer’s Disease (AD), are generated by the deposition of amyloid-beta (Aβ), the proteolytic product of amyloid precursor protein (APP), by β and γ-secretase." (PMID 32722509, 2020). "Amyloid β (Aβ) peptides generated via sequential β- and γ-secretase processing of the amyloid precursor protein (APP) are major etiopathological agents of Alzheimer’s disease (AD)." (PMID 32098349, 2020). "An in-depth investigation of ADAM9 protein or mRNA levels in human subjects with APP-related disorders, such as Alzheimer’s disease and autism spectrum disorder, has yet to be performed." (PMID 32612155, 2020). "Fe65 is an adaptor protein extensively analyzed in the context of Alzheimer’s disease because it binds to the amyloid precursor protein (APP) intracellular domain." (PMID 33192315, 2020). "This manuscript describes the effect of feeding Angiotensin Converting Enzyme Inhibitor (Captopril) and Angiotensin Receptor Blocker (Losartan), both inhibitors of the renin angiotensin system, to APP-related Drosophila models of Alzheimer’s Disease." (PMID 33060184, 2020). "Minocycline leads to improved outcomes in a mouse model of atherosclerosis, the transgenic APP/presenilin mouse model of Alzheimer's disease, the MPTP mouse model of Parkinson disease and after whole‐body γ‐irradiation in mice to name a few." (PMID 33145977, 2020). "For example, using Cas9 to knock-out the expression of mutant amyloid precursor protein (APP) was demonstrated to have neuroprotective effects in a mouse model of Alzheimer’s disease." (PMID 33027946, 2020). "APP is the parent protein that is processed by secretases to produce amyloid-β (Aβ), which is the most prevalent protein found in the senile plaques of Alzheimer’s disease, as well soluble APP alpha (sAPPα), which is elevated in autism." (PMID 32612155, 2020). "Further, alteration of Tip60 epigenetic mediated control in the brain by either APP or Aβ driven Alzheimer’s disease pathology leads to repression of a set of neuronal genes critical for synaptic function." (PMID 33304239, 2020). "Cumulative neuroimaging and autopsy studies of DS patients showed typical pathological manifestation of the early onset of Alzheimer disease (AD), which is consistent with the direct result of APP gene-dosage effects." (PMID 32820178, 2020). "It has been reported that activation of WNT signaling rescues memory loss and improves synaptic dysfunction in mouse models of Alzheimer’s disease, such as the SMAP8 mouse and the APP/PS1-transgenic mouse." (PMID 32635647, 2020). "Using the APPswe/PS1dE9 (APP/PS1) mouse model of Alzheimer's disease, we utilized the Morris water maze spatial learning paradigm to systematically evaluate mild behavioral deficits that occur during the early stages of disease pathogenesis." (PMID 33384577, 2020). "APP is the precursor for Aβ, a major constituent of amyloid plaques found in the brain of patients with Alzheimer’s disease." (PMID 32987857, 2020). "Genetic ablation of the p66Shc has been shown to reverse cognitive deficits and improve mitochondrial function in an APP transgenic mouse model of Alzheimer's disease." (PMID 32382538, 2020). "The last drug, RO-90-7501, targets the amyloid precursor protein (APP) gene and is an amyloid-β42 aggregation inhibitor and candidate Alzheimer’s disease molecule." (PMID 32291351, 2020). "This is supported by evidence from a mouse model of Alzheimer's disease (Transgenic human APP mouse), where increased PLA2 activity and AA levels were observed." (PMID 33584282, 2020). "Many of the known key players in Alzheimer’s disease, such as APP, are differentially expressed between tissue types and between different regions of the brain." (PMID 31947790, 2020). "It has been demonstrated that physical exercise and probiotic supplementation delay the progress of Alzheimer’s Disease (AD) in male APP/PS1TG mice." (PMID 32812166, 2020).
Alzheimer disease (continued). "In vivo studies were performed in an Alzheimer Disease animal model—APP double transgenic (Tg) 5xFAD—as well as in 5xFAD crossed with Tau transgenic 5xFADXTau (FT), which exhibit declined cognitive reduction at four months of age." (PMID 32380752, 2020). "APP is one of the most important Down syndrome candidate gene, whose triplication is responsible for neurodegeneration and early onset Alzheimer disease in individuals with Down syndrome." (PMID 32994493, 2020). "For example, β-site amyloid precursor protein (APP)-cleaving enzyme 1-antisense (BACE1-AS) stabilizes BACE1 RNA and promotes APP cleavage, which is actively involved in the pathogenesis of Alzheimer’s disease." (PMID 32035423, 2020). "The amyloid precursor protein (APP) in Alzheimer’s disease (AD) pathology is modified by O-GlcNAcylation." (PMID 32349769, 2020). "In fact, APP is located on chromosome 21, and people with Down’s syndrome, who harbor three copies of APP, develop the typical neuropathology of Alzheimer’s disease at a young age." (PMID 33260956, 2020). "Understanding the biological function of amyloid beta (Aβ) precursor protein (APP) beyond its role in Alzheimer’s disease is emerging." (PMID 32576936, 2020). "A similar phenomenon is observed in neurons overexpressing amyloid precursor protein (APP) or neurons form the 5XFAD Alzheimer disease mouse model that express high levels of amyloid-β42." (PMID 32486187, 2020). "Several mouse models have been generated with genetic mutations related to human amyloid precursor protein (APP), C-terminal fragment of APP, Aβ, and familial forms of Alzheimer’s disease, which result in robust Aβ accumulation." (PMID 33014535, 2020). "For example, APP in the M1 module is involved in neural growth and maturation during brain development, and it plays a critical role in the pathology of Alzheimer’s disease." (PMID 33086708, 2020). "Familial Alzheimer's disease (FAD) is caused by a dominant inherited mutation of presenilins (PSs; PS1 and PS2) and amyloid-β (Aβ) precursor protein (APP; Chakroborty and Stutzmann, 2014)." (PMID 33424550, 2020). "APP and its cleavage products, including the Aβ peptides, are mainly known for their putative roles in Alzheimer’s disease (AD), the most common dementia and primary neurodegenerative disorder in elderly persons." (PMID 32906646, 2020). "The unsupervised approach resulted in a 238 gene network, including the Alzheimer’s disease gene APP (Amyloid Beta Precursor Protein) as an exception node, and several novel candidate genes." (PMID 32327964, 2020). "The two major proteins involved in Alzheimer’s disease (AD) are the amyloid precursor protein (APP) and Tau." (PMID 32380752, 2020). "Alzheimer’s disease (AD) is a neurodegenerative disorder characterized by cognitive decline and amyloid-beta (Aβ) depositions generated by the proteolysis of amyloid precursor protein (APP) in the brain." (PMID 32469963, 2020). "These anthocyanins also prevented apoptosis and neurodegeneration by suppressing the apoptotic and neurodegenerative markers in the amyloid precursor protein/presenilin-1 (APP/PS1) mouse model of Alzheimer’s disease (AD)." (PMID 32887513, 2020). "Cleavage of amyloid precursor protein (APP) by BACE‐1 (β‐site APP cleaving enzyme 1) is the rate‐limiting step in amyloid‐β (Aβ) production and a neuropathological hallmark of Alzheimer's disease (AD)." (PMID 32323475, 2020). "Early endosomes represent the first station of internalization and processing of the Alzheimer’s disease (AD)-related amyloid-β precursor protein (APP)." (PMID 31992816, 2020). "Aβ deposition is a central event in Alzheimer’s disease (AD), but alterations of APP physiological functions are likely to play a key role in the pathogenesis." (PMID 32327470, 2020). "The amyloid-β (Aβ) peptide, the primary constituent of amyloid plaques found in Alzheimer’s disease (AD) brains, is derived from sequential proteolytic processing of the Amyloid Precursor Protein (APP)." (PMID 31915042, 2020).
Alzheimer disease (continued). "The amyloid precursor protein (APP) plays a central role in Alzheimer’s disease (AD), as it is processed into different proteolytic products, including the toxic Aβ peptide, accumulating in AD brain tissue." (PMID 32065241, 2020). "Endosomal trafficking and amyloidogenic cleavage of amyloid precursor protein (APP) is believed to play a role in the neurodegeneration observed in Alzheimer’s disease (AD)." (PMID 32731849, 2020). "APP has been known as central to the pathogenesis of Alzheimer's disease (AD) and has been confirmed as the potential biomarker in predicting brain amyloid-β burden." (PMID 32724827, 2020). "The human β-amyloid precursor protein (APP): its structure, and its cellular roles as well as its proteolytic processing are in the focus of intensive research due to the central role of APP during the development of Alzheimer's disease (AD)." (PMID 32341983, 2019). "Reduction of KLC1 levels has been shown to impair APP axonal transport in rodent and Drosophila neurons and to exacerbate Alzheimer’s disease phenotypes." (PMID 31806024, 2019). "In APP/PS1 double transgenic mice (with features of Alzheimer’s disease), diet-induced obesity worsened amyloid burden and cognitive performance." (PMID 31130848, 2019). "The relevance of these gradients for glial plasticity in Alzheimer’s disease was nicely illustrated in a mouse model of familial Alzheimer’s disease (APPswe/PS1dE9 mice, or APP/PS1 mice) characterized by aging-dependent plaque formation." (PMID 31780897, 2019). "Long-term dietary choline supplementation (from 2.5 to 10 months) in an APP/PS1 (PS1 = Presenelin1) mouse model of Alzheimer’s disease reduced the accumulation of amyloid plaques and reduced APP processing in the mouse hippocampus." (PMID 31817768, 2019). "Understanding how APP is transported through axons and how this transport is regulated are therefore important aspects of Alzheimer’s disease research." (PMID 31806024, 2019). "We have also compared differences in the F-actin distribution in individual synapses between WT and a transgenic model for Alzheimer’s disease (APP/PS1)." (PMID 31311803, 2019). "Alzheimer’s disease is characterized by the presence of extracellular toxic plaques of amyloid β (Aβ) peptides, proteolytic fragments of the amyloid precursor protein (APP)." (PMID 31671891, 2019). "Amyloid precursor protein (APP) transgenic animal models of Alzheimer’s disease have become versatile tools for basic and translational research." (PMID 30853883, 2019). "Tau and APP in microvesicles separated patients with Alzheimer’s disease from controls with an AUC of 0.84 and 0.89 respectively." (PMID 31068645, 2019). "Prior to being used in mouse lemurs, the Alzheimer’s disease and control brains were inoculated in the hippocampus of APP/PS1dE9 and Tau30+/+ mouse models of β-amyloid and tau lesions." (PMID 31481130, 2019). "Damage to axonal transport of APP has therefore been proposed to induce a toxic cycle of events that eventually lead to neuronal cell death in Alzheimer’s disease." (PMID 31806024, 2019). "MiRNAs are involved in many aspects of Alzheimer’s disease progression including direct regulation of APP expression, alternative splicing of APP, regulation of BACE, regulation of Tau and even lipid metabolism." (PMID 31022830, 2019). "The formation of amyloid plaques in Alzheimer’s disease starts with hydrolysis of the APP protein in its beta site by the protease BACE1 (Beta-secretase 1)." (PMID 30871545, 2019). "It has been reported that miR-342-5p is upregulated in Alzheimer’s disease (AD) transgenic mouse models, including APP/PS1, PS1DE9, and PS1-M146V lines." (PMID 31288473, 2019). "The first-ranked gene FMR1 was proved to be associated with mental diseases like mental retardation and autism, and five other genes (APP, SNCA, MAPT, SIRT2, APOE) are known to be associated to Alzheimer's disease." (PMID 32038710, 2019).